MIR4787 (microRNA 4787)
Synonyms: hsa-mir-4787; mir-4787
Gene: MicroRNA gene on chromosome 3 (50,675,080 to 50,675,163, forward strand). Ensembl gene ENSG00000272543.
Homologues: Orthologues: chimpanzee MIR4787 (100% identical).